AR (androgen receptor)
Diseases named in the same sentence as AR in open-access papers (continued):
Sharing a sentence is not in itself a finding about the gene and the disease.
gastric cancer (continued). "Additionally, recent research has discovered that AR activation leads to increased expression of LAMA4, which in turn induces resistance to cisplatin in gastric cancer cells, highlighting a potential mechanism by which AR contributes to treatment resistance." (PMID 41228208, 2025). "In addition, AR was frequently overexpressed in gastric cancer tissues compared with normal gastric mucosa." (PMID 41228208, 2025). "We further observed that FGFR2 fusion models, including gastric cancer cell lines, were sensitive to CA3 inhibition, and surprisingly, CA3 exposure was associated with upregulation of an androgen receptor associated transcriptional signature in the tested CCA and gastric cancer models." (PMID 39300603, 2024). "Androgen receptor (AR) expression is pivotal in gastric cancer initiation and advancement." (PMID 38667536, 2024). "Therefore, it can be stated that bicalutamide is able to downregulate the androgen receptor (AR)/miR-125 pathway and induce apoptosis of cells from gastric cancer." (PMID 37511303, 2023). "In short, hsa-miR-942-3p may be a potential prognostic marker of gastric cancer related to the AR and mitogen-activated protein kinase (MAPK)/extracellular signal-regulated kinase (ERK) signaling pathways." (PMID 36135175, 2022). "In addition, PTGER3 can also up-regulate the expression of related MMP2 and AR to promote the proliferation of cancer cells and the deterioration of gastric cancer." (PMID 34646828, 2021). "Since it has been shown that AR overexpresses in Gastric Cancer (GC) as a male-predominant tumor, the goal of this study was to evaluate whether AR could regulate ZEB1 expression in GC." (PMID 32153739, 2020). "Additionally, this study provides a clue about the functional interaction between ZEB1 and AR signaling pathways in gastric cancer." (PMID 32153739, 2020). "Moreover, our study provided evidence elucidating a novel promising marker, simultaneous evaluation of AURKA and AR expression, which properly predict prognosis of gastric cancer patients." (PMID 31871591, 2019). "Recently, some studies have devoted on indicating the oncogenic role of AR in gastric cancer." (PMID 31871591, 2019). "Additionally, the roles of progesterone receptor (PR) and androgen receptor (AR) in gastric cancer are poorly defined." (PMID 23199240, 2012). "The high incidence of male gastric cancer may be due to AR signaling pathway regulation." (PMID 39256355, 2024). "There is a male preponderance in gastric cancer (GC), which suggests a role of androgen and androgen receptor (AR)." (PMID 33947843, 2021). "Since the identification of proper markers that precisely predict aggressiveness of gastric cancer could improve the survival of these patients by managing their treatments, we asked if combined evaluation of AR and AURKA expression could introduce a proper prognostic marker." (PMID 31871591, 2019). "Despite the mounting studies exploring the role of estrogen receptor alpha (ERα), estrogen receptor beta (ERβ) and androgen receptor (AR) in gastric cancer (GC), there remain controversies in those findings." (PMID 28388558, 2017). "However, ERα, PR and AR immunostaining was mainly localized in the cytoplasm while ERβ immunostaining was ubiquitously observed in the nucleus for both normal epithelium and gastric cancer cells." (PMID 23199240, 2012). "RNA sequencing of gastric cancer and CCA models demonstrated upregulation of an androgen receptor–mediated transcriptional program following exposure to CA3 in five unique models tested." (PMID 39300603, 2024). "Then, using the network pharmacology method, the proliferation of gastric cancer was inhibited by the oridonin through 11 signalling pathways, among which TNF‐α, AR and TGF‐β signalling pathways were the three most important signalling pathways." (PMID 37431884, 2023).
gastric cancer (continued). "Overall, we suggest that LOC441461 modulates gene transcription, inducing the malignancy of gastric cancer by interacting with RELA, IRF1, ESR1, AR, POU5F1, TRIM28, and GATA1." (PMID 35267457, 2022). "In gastric cancer, LAMA4 is activated by the androgen receptor and enhances cell cisplatin resistance." (PMID 36539799, 2022). "The interaction of the transcription factors RELA, IRF1, ESR1, AR, POU5F1, TRIM28, and GATA1 with LOC441461 affected the degree of the malignancy of gastric cancer by modulating gene transcription." (PMID 35267457, 2022). "The present study investigated the expression of ERα, ERβ and AR in Chinese gastric cancer by immunohistochemistry, analyzed their clinical relevance in gastric cancer, and examined the potential mechanisms by which ERα and AR modulated GC progression." (PMID 28388558, 2017). "Experimental studies confirmed that the proliferation inhibition of oridonin on SGC‐7901 cell was related to TNF‐α/AR/TGF‐β signalling pathway axis, which confirmed the prediction of network pharmacology, and elucidated the mechanism of oridonin on gastric cancer." (PMID 37431884, 2023). "Just as we expected, positive expression of ERα and AR correlates with favorable outcome for gastric cancer patients though they are not independent prognostic factors." (PMID 23199240, 2012). "Moreover, androgen receptor inhibitors and HER2 inhibitors may be used against different tumor types, including breast, colon, and gastric cancer." (PMID 35648382, 2023). "The expression of ERα and AR were not independent prognostic factors for gastric cancer." (PMID 23199240, 2012). "However, ERα and AR were not independent prognostic factors for gastric cancer when multivariate survival analysis was performed." (PMID 23199240, 2012). "Amongst the 7 cases initially selected as gastric carcinoma, six did not display nuclear immunoreactivity for AR; however, one case belonging to a female patient showed moderate to strong positive nuclear staining with AR in 60% of the nuclei." (PMID 17020615, 2006).
salivary duct carcinoma (48 papers, 2006 to 2026). An aggressive, high grade adenocarcinoma that arises from the salivary glands. "A subgroup of salivary duct carcinoma (SDC) harbor overexpression of the androgen receptor (AR), and co-occurring mutations in the HRAS- and PIK3CA-genes." (PMID 37427101, 2023). "After review of final histopathological diagnoses, 4 patients had salivary duct carcinoma with AR expression and HRAS/PIK3CA mutation and were included in the analysis." (PMID 37427101, 2023). "It has been shown that AR overexpression is most frequently associated with salivary duct carcinomas." (PMID 30382367, 2019). "Salivary duct carcinoma normally expresses the AR, but a subset was shown to have higher levels of HER2 that corresponded to low or absent AR expression." (PMID 40906535, 2025). "The focal AR expression (present in 10% of tumor cells) suggests the presence of a salivary duct carcinoma-like subpopulation arising during malignant progression, although this does not represent the dominant phenotype." (PMID 41404066, 2025). "One salivary gland tumor showed poorly cohesive large epithelioid cells with prominent background inflammation and expressed AR and GATA3, in line with a possible salivary duct carcinoma variant." (PMID 39387893, 2025). "Salivary duct carcinoma (SDC) exhibits diffuse strong AR and HER2 positivity, comedo-necrosis, and lacks a lymphoid background." (PMID 41404066, 2025). "For example, HER2 and androgen receptor positivity in salivary duct carcinoma and the ETV6-NTRK3 fusion in secretory carcinoma are important for treatment planning." (PMID 40002255, 2025). "GFAP-15, human epidermal growth factor (HER2) and androgen receptors (AR) are frequently positive markers in salivary duct carcinomas, but some authors consider their specificity questionable." (PMID 38929710, 2024). "AR positive adenocarcinomas were similarly to salivary duct carcinoma targeted with ADT therapy in clinical trials, while HER2 amplified tumours demonstrated enhanced sensitivity to T-DM1 therapy." (PMID 37439929, 2023). "Scoring AR pathway activity has been successfully used to stratify response to hormone therapy in hormone-sensitive AR-positive salivary duct carcinoma (SDC)." (PMID 37240349, 2023). "The salivary duct carcinoma characterize in high overexpression (78–96%) of androgen receptor (AR) and the treatment has been already supported with androgen-deprivation therapy (ADT; with goserelin)." (PMID 37439929, 2023). "In vitro studies using salivary duct carcinoma-derived cells showed that depletion of AR using siRNA inhibits cell growth, but cell proliferation is unaltered in steroid-depleted media." (PMID 37626712, 2023). "The only exception is AR+ salivary duct carcinomas, for which several clinical trials have shown an advantage in using the new generation of nonsteroidal antiandrogens in terms of a higher response rate and a better prognosis and clinical outcome." (PMID 36835177, 2023). "This is, to the best of our knowledge, the largest clinical case series of AR+, PIK3CA/HRAS co-mutated salivary duct carcinoma." (PMID 37427101, 2023). "In a previous study, all six cases of salivary duct carcinoma and 14 cases of carcinoma ex pleomorphic adenoma (a subset of salivary gland carcinoma) showed strong nuclear immune reactivity for AR." (PMID 35517428, 2022). "There are clinical trial data showing the efficacy of either androgen deprivation therapy with bicalutamide and enzalutamide and combined androgen blockade with bicalutamide and triptorelin in recurrent or metastatic AR-overexpressing salivary duct carcinoma." (PMID 35267442, 2022). "They studied the application of ADT in 35 patients with androgen receptor-positive advanced salivary duct carcinoma, which lead to a median overall survival (OS) of 17 months versus 5 months in 43 patients receiving best supportive care." (PMID 33296026, 2021).
salivary duct carcinoma (continued). "The association between EZH2 or H3K27me3 expression and clinical outcomes in patients with salivary duct carcinoma treated with AR- or HER2-targeted therapy." (PMID 35186711, 2021). "Androgen deprivation therapy (ADT) is a leading treatment strategy in the palliative care of patients with androgen receptor (AR)‐positive salivary duct carcinoma (SDC)." (PMID 31745978, 2020). "Androgen deprivation therapy (ADT) is first‐line palliative treatment in androgen receptor‐positive (AR+) salivary duct carcinoma (SDC), and response rates are 17.6–50.0%." (PMID 31745978, 2020). "In several studies, the AR positivity was shown in 64–77% of all salivary duct carcinoma and 5% of ACC cases." (PMID 30382367, 2019). "There is first moderate evidence that patients with androgen receptor positive salivary duct carcinoma, known to be a phenotype with bad prognosis, seem to profit from an androgen deprivation therapy." (PMID 29868604, 2018). "Due to similar nature of salivary duct carcinoma and breast ductal carcinoma, over-expression of androgen receptor, human epidermal growth factor receptor 2 (HER-2)/neu proto-oncogene has also been studied." (PMID 30345196, 2018). "AR overexpression is most frequently associated with salivary duct carcinomas (SDC), the majority of which are positive for AR." (PMID 28208703, 2017). "Recent molecular studies have shown evidence of androgen receptor signaling in several types of salivary gland cancer, mainly salivary duct carcinoma." (PMID 28208703, 2017). "The use of hormone therapy and anti-HER2 therapy for salivary duct carcinoma or AR+/HER2+ adenocarcinoma is a treatment approach that should continue to be refined and investigated." (PMID 31093341, 2016). "However, while androgen receptor expression has been noted in some salivary gland malignancies such as salivary duct carcinoma, there is scant evidence of ER or PR playing a role in MEC pathogenesis." (PMID 40755711, 2025). "Salivary duct carcinoma (SDC) is a rare and aggressive malignancy with a generally dismal prognosis and no standard of care established, despite a known association with epidermal growth factor receptor 2 (HER2) and androgen receptor (AR) over‐expression." (PMID 39814370, 2025). "It is well-known that salivary duct carcinoma often expresses AR and HER2." (PMID 40938457, 2025). "Androgen receptor (AR) overexpression is frequently seen in salivary duct carcinoma." (PMID 39330047, 2024). "This targeted therapy may be considered in patients with salivary duct carcinoma with androgen receptor expression and HER2neu amplification according to individual risk factors." (PMID 34427717, 2022). "In addition to HER2, the androgen receptor (AR) is overexpressed in most patients with salivary duct carcinoma (SDC)." (PMID 35267442, 2022). "For example, in androgen receptor overexpressing salivary duct carcinoma, there are pre-clinical studies showing AR-dependency in cultured salivary duct carcinoma cell lines and phase 2 data for combined androgen blockade which is being adopted as a standard of care." (PMID 34503145, 2021). "Androgen receptor signaling seems pivotal in aggressive salivary duct carcinoma." (PMID 34298742, 2021). "Salivary duct carcinomas may overexpress Her-2 and androgen receptor, with promising clinical outcomes after exposure to targeted therapies approved for other indications." (PMID 33194707, 2020). "Based on nuclear findings, it may be possible to distinguish salivary duct carcinoma from other high-grade salivary gland carcinomas, by immunostaining for androgen receptor, gross cystic disease fluid protein-15 and p63." (PMID 30345196, 2018). "AR positivity has also been documented in salivary duct carcinomas [S1, S4-S6]." (PMID 25595907, 2015). "AR has also been detected by IHC in 90% of salivary duct carcinomas." (PMID 17020615, 2006). "Histology confirmed salivary duct carcinoma ex pleomorphic adenoma (T4N3bM0, HER2+, AR–, Ki-67 60–80%)." (PMID 40364166, 2025).
salivary duct carcinoma (continued). "However, carcinomas may frequently display a diffuse oncocytic phenotype, being classified by their characteristic features (e.g., AR-positive salivary duct carcinoma, MEC with MAML2 rearrangements, secretory carcinoma with ETV6 NTRK3 gene fusion, and DOG1- and SOX10-positive acinic cell carcinoma)." (PMID 41440486, 2025). "In salivary duct carcinoma (SDC), therapies targeting human epidermal growth factor receptor 2 (HER2) and androgen receptor (AR) have shown promising clinical efficacy." (PMID 38539539, 2024). "At the protein level, nuclear AR has been detected in 70% to 98% of nonsquamous salivary duct carcinoma (SDC) cases, with a higher prevalence observed in men." (PMID 41486951, 2026). "This tumor showed, in addition, overlap with poorly cohesive salivary duct carcinoma, a possibility further enhanced by reactivity for AR and GATA3, but not p40." (PMID 39387893, 2025). "In the same line, a high-grade salivary gland tumor composed of expansile, centrally necrotic nests composed of AR-positive and S100-negative apocrine-type cells with an ETV6::NTRK3 fusion was recently interpreted as salivary duct carcinoma with an unusual genetic background." (PMID 37415052, 2023). "Overexpression of human epidermal growth factor receptor type 2 (HER2) occurs in almost 25-30% of androgen receptor (AR)-positive salivary gland carcinomas (SGCs), notably salivary duct carcinoma (SDC) and adenocarcinoma not otherwise specified (NOS)." (PMID 36733354, 2022). "Salivary duct carcinoma (SDC) is an aggressive subtype of salivary gland cancer, which is often androgen receptor (AR) positive (66.7–96.4%).1, 2, 3 Primary treatment consists of a tumor resection, most often in combination with a neck dissection and postoperative radiotherapy." (PMID 31745978, 2020). "Androgen receptor immunostain was positive in salivary duct carcinoma, while p63 was negative." (PMID 35092649, 2022). "Androgen deprivation therapy has demonstrated efficacy in cases of salivary duct carcinoma (SDC) and high-grade adenocarcinoma not otherwise specified (NOS) that express androgen receptor." (PMID 31428578, 2019). "Specific pathologic types, notably salivary duct carcinoma (SDC) and adenocarcinoma not otherwise specified (NOS) may overexpress androgen receptors (AR)." (PMID 36733354, 2022).